PLA1A (phospholipase A1 member A)
Diseases named in the same sentence as PLA1A in open-access papers:
PLA1A is named in the same sentence as 47 diseases in open-access papers, as found by Europe PMC text mining. Sharing a sentence is not in itself a finding about the gene and the disease. The quoted sentences say what the papers report.
systemic lupus erythematosus (6 papers, 2021 to 2026). An autoimmune multi-organ disease typically associated with vasculopathy and autoantibody production. "Increased PLA1A plasma/serum levels were associated with various autoimmune disorders, such as systemic lupus erythematosus and early diagnosed rheumatic arthritic (RA)." (PMID 35955693, 2022). "The serum PLA1A level is associated not only with tumorigenesis, but also to most inflammatory diseases, including systemic lupus erythematosus, hepatitis, and hyperthyroidism." (PMID 33723350, 2021). "In this regard, serum PLA1A has been identified as a biomarker of systemic lupus erythematosus disease activity." (PMID 41212150, 2026). "Bronchoalveolar lavage fluids from certain allergic asthma patients, serum of melanoma subjects, Graves’ disease patients, and systemic lupus erythematosus (SLE) patients contain elevated levels of PLA1A." (PMID 34884486, 2021). "To investigate the possible implication of PLA1A during rheumatic diseases, we monitored PLA1A in synovial fluids from patients with rheumatoid arthritis and plasma of early-diagnosed arthritis (EA) patients and clinically stable systemic lupus erythematosus (SLE) patients." (PMID 34884486, 2021).
melanoma (4 papers, 2021 to 2024). A malignant, usually aggressive tumor composed of atypical, neoplastic melanocytes. "Demonstrating impressive diagnostic performance, PLA1A effectively distinguishes BRAF-mutated melanoma samples with a sensitivity of 62% and specificity of 61%." (PMID 39582535, 2024). "The analysis based on specimen types indicated that PLA1A had a relatively accurate diagnostic value in discriminating the naïve melanoma samples from advanced melanoma samples, with a sensitivity of 0.91 and specificity of 0.57." (PMID 33723350, 2021). "Increasing mRNA and serum PLA1A levels are significantly associated with different clinical stages of melanoma, which suggests the potential involvement of the PS PLA1/lysophosphatidylserine axis in melanoma pathogenesis." (PMID 33723350, 2021). "Therefore, the aim of this study was at first to investigate the diagnostic value of PLA1A in melanoma patients at different stages and with different mutations to confirm the diagnostic value of PLA1A during melanomagenesis." (PMID 33723350, 2021). "The evidence to consider PLA1A as a diagnostic marker were shown, which could help to distinguish naïve melanoma samples from advanced melanoma samples." (PMID 33723350, 2021). "However, a further clinical confirmation is needed to determine the diagnostic and prognostic value of PLA1A levels in melanoma, as well as to establish which patients need more aggressive therapy." (PMID 33723350, 2021). "Additionally, the correlation between histopathological subtypes of BRAF/NRAS-mutated melanoma and PLA1A was analyzed." (PMID 33723350, 2021). "Despite numerous experimental studies, the diagnostic and prognostic values of PLA1A among different mutant melanoma patients and PLA1A role in melanomagenesis remain unknown." (PMID 33723350, 2021). "Therefore, the diagnostic value of PLA1A in BRAF and NRAS-mutated samples of melanoma patients was investigated to confirm the diagnostic utility of PLA1A during melanomagenesis." (PMID 33723350, 2021). "Moreover, a comprehensive investigation positions PLA1A as a robust diagnostic marker for melanoma." (PMID 39582535, 2024). "Collectively, DMKN and PLA1A present themselves as promising candidates for personalized therapy, shedding light on their multidimensional roles in shaping the melanoma phenotype in tailored treatment strategies." (PMID 39582535, 2024). "Remarkably, PLA1A levels exhibit a significant elevation during melanogenesis, particularly in BRAF-mutated melanoma cases." (PMID 39582535, 2024). "PLA1A mRNA and serum levels were significantly higher in patients with BRAF-mutated melanoma compared to the patients with NRAS-mutated melanoma." (PMID 33723350, 2021). "By considering both PLA1A mRNA and serum levels simultaneously, PLA1A levels were significantly increased in BRAF/NRAS+ melanoma patients (p ≤ 0.05)." (PMID 33723350, 2021). "As expected, melanoma patients with PLA1A1-high tumors had significantly shorter DFS compared to that in patients with PLA1A-low tumors (5-year DFS rate: 69.3% vs 75.4%, p = 0.026)." (PMID 33723350, 2021). "In general, higher PLA1A levels were correlated with disease severity and metastatic lesions among patients with melanoma." (PMID 33723350, 2021). "Our findings suggest that PLA1A can be considered as a potential diagnostic marker for advanced and BRAF-mutated melanoma." (PMID 33723350, 2021). "Moreover, the paper explores potential druggable targets for melanoma patients, including ERK5, CD73, ALDH1A1, PLA1A, and DMKN, which hold promise in addressing diagnostic hurdles and guiding personalized therapeutic decisions." (PMID 39582535, 2024). "Interestingly, the average PLA1A expression was consistently and significantly higher in tissues of metastatic melanoma (n = 15) compared to naïve/control melanoma samples (n = 10)." (PMID 33723350, 2021).
melanoma (continued). "Similar to the results from BRAF+ melanoma patients, serum PLA1A levels were increased in MUT-NRAS melanoma patients compared to the level in the WT-NRAS (36.25 ± 16.24 μg/L vs 29.56 ± 14.26 μg/L), although this difference was not statistically significant (p > 0.05)." (PMID 33723350, 2021). "Because of the poor 5-year survival rate and prognosis of patients with late stage melanoma, PLA1A, in conjunction with S-100 and HMB-45, could serve as a novel marker to distinguish lymph node naive melanoma from melanoma metastasis." (PMID 33723350, 2021). "In addition, PLA1A levels were significantly higher in primary melanoma tissues (n = 12) compared to naïve/control melanoma samples." (PMID 33723350, 2021). "Furthermore, PLA1A is a potential diagnostic marker for advanced and BRAF mutant melanoma." (PMID 38357546, 2024). "Importantly, the high sensitivity, specificity, and AUC in BRAF-MUT advanced melanoma samples suggested that PLA1A could be used as a marker for an effective prediction of advanced BRAF-mutant melanoma cancer." (PMID 33723350, 2021). "Therefore, a significant relationship exists between PLA1A levels and melanoma stage." (PMID 33723350, 2021). "Therefore, as a main member of PLA1 during melanogenesis, both PLA1A mRNA expression and serum levels were measured in our collected melanoma tissues and serum using quantitative Real-time PCR analysis (qRT-PCR) and enzyme-linked immunosorbent assay (ELISA), respectively." (PMID 33723350, 2021). "Moreover, PLA1A had the highest sensitivity, specificity, and AUC in BRAF-MUT advanced melanoma samples, suggesting that PLA1A could be used as a marker for an effective prediction and diagnosis of advanced BRAF-mutant melanoma cancer." (PMID 33723350, 2021). "As no therapeutic agents have been approved specifically for NRAS-mutant melanoma, our aim was to compare the benefit of PLA1A in the BRAF- and NRAS-driven melanoma cancer population." (PMID 33723350, 2021). "In this regards, single-site biopsy of PLA1A could be considered as a diagnostic marker of BRAF-mutant metastasis in melanoma cancer, since it is sufficiently sensitive and precise in distinguishing melanoma patients with BRAF-mutated and NRAS-mutated advanced melanoma." (PMID 33723350, 2021). "Interestingly, this is the first report demonstrating that PLA1A mRNA expression, with a cut-off value of 0.072 and serum PLA1A levels of 40.91 μg/L could be used to discriminate naïve melanoma samples from advanced melanoma samples, with a sensitivity of 91% and a specificity of 57%." (PMID 33723350, 2021). "Since PLA1A can be positive in more than 50 cases that are HMB-45, S-100 and Ki-67 positive, it can be a useful component in the diagnosis of metastasis melanomas by immunohistochemistry." (PMID 33723350, 2021). "Notably, PLA1A can be used as a diagnostic marker for an efficient discrimination between naïve melanoma samples and advanced melanoma samples (sensitivity 91%, specificity 57%, and AUC 0.99), as well as BRAF-mutated melanoma samples (sensitivity 62%, specificity 61%, and AUC 0.75)." (PMID 33723350, 2021). "In addition, a significant difference in the increased PLA1A positive cells was found between advanced BRAF/NRAS-MUT melanoma stages and naïve/control melanoma samples." (PMID 33723350, 2021). "Our finding showed for the first time that PLA1A with the highest sensitivity, specificity, and AUC could be used as a single indispensable marker for diagnosis, screening, and prognosis in BRAF-MUT advanced melanoma." (PMID 33723350, 2021). "For instance, high PLA1A expression was reported in the airway epithelium in asthma, in vascular endothelial cells of heart transplant rejection, as well as in non-metastasis melanoma cell lines and prostate cancer tissues." (PMID 34884486, 2021).
Arthritis (2 papers, 2021 to 2022). Inflammation of a joint. "PLA1A deficiency reduced susceptibility to induced arthritis and cutaneous inflammation in the MIP model." (PMID 35955693, 2022). "PLA1A might contribute to the development of arthritis in the MIP model by promoting IL-17-producing cells since PLA1A deficiency was associated with a lower level of IL-17." (PMID 35955693, 2022).
autoimmune disease (2 papers, 2021 to 2022). A disorder resulting from loss of function or tissue destruction of an organ or multiple organs, arising from humoral or cellular immune responses of the individual to their own tissue constituents. "High PLA1A serum level and tissue expression are associated with cancer metastasis, acute coronary syndrome, and autoimmune diseases, such as SLE." (PMID 34884486, 2021). "To better understand the role of PLA1A in inflammation and gain insight into how PLA1A contributes to the pathogenesis of autoimmune diseases, we characterized the Pla1a−/− mice and assessed the implication of Pla1a in the development of MIP." (PMID 35955693, 2022). "Differences in PLA1A concentration between active autoimmune disease and steady or non-autoimmune disease were also remarkable, as highlighted in a previous clinical study with SLE patients." (PMID 34884486, 2021).
Cirrhosis (2 papers, 2017 to 2021). A chronic disorder of the liver in which liver tissue becomes scarred and is partially replaced by regenerative nodules and fibrotic tissue resulting in loss of liver function. "The serum PLA1A level in patients with liver injury (hepatitis, cirrhosis) was increased in comparison to that of healthy subjects." (PMID 34884486, 2021).
psoriatic arthritis (2 papers, 2021 to 2022). Joint inflammation associated with psoriasis. "We generated Pla1a−/− mice to assess their phenotype and the impact of PLA1A deficiency on the development of mannan-induced psoriatic arthritis (MIP)." (PMID 35955693, 2022). "Synovial fluids from rheumatoid and psoriatic arthritis patients have high levels of PLA1A." (PMID 35955693, 2022). "PLA1A levels in synovial fluid from RA and psoriatic arthritis (PsA) patients were elevated." (PMID 35955693, 2022).
rheumatic diseases (2 papers, 2021 to 2022). "The current study was to understand PLA1A functions in the pathophysiology of rheumatic diseases." (PMID 35955693, 2022).
acute coronary syndrome (1 paper, 2021). Signs and symptoms related to acute ischemia of the myocardium secondary to coronary artery disease. "PLA1A has been associated with cancer metastasis, asthma, as well as acute coronary syndrome." (PMID 34884486, 2021). "Serum PLA1A significantly correlated with plasma lysoPS level in culprit coronary arteries from acute coronary syndrome patients and in ascites from gastric cancer patients." (PMID 34884486, 2021).
breast carcinoma (1 paper, 2020). "Other genes selected by Rlogreg, namely KISS1, IGF2BP2, CALCA, PLA1A, and FAM171A1, have been reported to be related to breast cancer or other types of cancer." (PMID 32795265, 2020).
coronary artery disease (1 paper, 2022). "PLA1 (Phospholipase A1 member A) hydrolyzes fatty acids at the sn-1 position of phosphatidylserine and 1-acyl-2-lysophosphatidylserine and its abnormal expression is associated with coronary artery disease (CAD) and MI." (PMID 36299582, 2022).
cutaneous melanoma (1 paper, 2021). A primary melanoma arising from atypical melanocytes in the skin. "As regard the prototypic testing of advanced cutaneous melanoma, PLA1A increased the hope in finding effective clinical markers for high TMB, and a potential cure." (PMID 33723350, 2021).
diabetes (1 paper, 2014). "The protein expression of PLA1A in the vitreous samples from PDR patients was increased by about 3.53-fold compared to control patients without diabetes." (PMID 25496321, 2014). "We demonstrated that PLA1A, AGK, S1PR1 and SPL were detected in all vitreous fluid samples from patients with PDR and control patients without diabetes." (PMID 25496321, 2014). "Western blot analysis was used to quantify the expression levels of PLA1A, PLA2, AGK, S1PR1, SPL and 5-lipoxygenase in vitreous fluid samples from patients with PDR (n = 16) and control patients without diabetes (n = 16)." (PMID 25496321, 2014).
glioma (1 paper, 2024). A benign or malignant brain and spinal cord tumor that arises from glial cells (astrocytes, oligodendrocytes, ependymal cells). "The invasion, metastasis, and worse prognosis of colorectal, glioma, and prostate cancer correlate with elevated PLA1A expression." (PMID 38357546, 2024).
gout (1 paper, 2021). A condition characterized by painful swelling of the joints, which is caused by deposition of urate crystals. "In synovial fluid samples, PLA1A was 35.08 ± 7.56 pg/mL in RA patients, 636.8 ± 521.4 pg/mL in PsoA patients, 10.04 ± 0.98 pg/mL in OA patients, and 18.74 ± 9.03 pg/mL in gout patients, respectively." (PMID 34884486, 2021). "High concentrations of PLA1A were also detected in synovial fluids from rheumatoid arthritis patients compared to those from osteoarthritis (OA) and gout patients." (PMID 34884486, 2021). "Compared to gout and the non-rheumatoid disease OA, the inflammatory synovial fluids of RA patients showed a higher concentration of PLA1A." (PMID 34884486, 2021).
Graves disease (1 paper, 2022). Graves' disease is an autoimmune disorder that leads to overactivity of the thyroid gland (hyperthyroidism).It is caused by an abnormal immune system response that causes the thyroid gland to produce too much thyroid hormones. "RA, SLE, and Graves’ disease patients show a high plasma level of PLA1A." (PMID 35955693, 2022).
hyperlipidemia (1 paper, 2025). "Notably, metabolic DEGs such as ACSL1, ABCA1, ABCG1, ACAT2, ALOX5AP, PLA1A, and PPARG were elevated in hyperlipidemia." (PMID 39853712, 2025).
metastatic melanoma (1 paper, 2021). A melanoma that has spread from its primary site to another anatomic site. "Our results revealed for the first time that the upregulation of PLA1A in the serum of advanced metastatic melanoma tissues represent an excellent diagnostic marker in BRAF/NRAS-driven melanomagenesis." (PMID 33723350, 2021). "In conclusion, our results showed that PLA1A might be a promising diagnostic marker in patients with advanced metastatic melanoma, providing a more accurate diagnostic marker for BRAF-mutant samples of MM patients." (PMID 33723350, 2021). "Thus, investigating multiple mRNA marker profiles would be beneficial to improve the sensitivity of PLA1A as a single diagnostic marker or as a novel component in the immunohistochemical panel of metastatic melanomas." (PMID 33723350, 2021). "A significant positive correlation was found between PLA1A and disease severity as well as diagnostic markers, thus PLA1A could be used in the future as a non-invasive marker in the diagnosis and therapy of metastatic melanomas." (PMID 33723350, 2021). "PLA1A expression was significantly increased during melanogenesis and positively correlated to disease severity and histopathological markers of metastatic melanoma." (PMID 33723350, 2021). "Notably, PLA1A was highly expressed in advanced metastatic melanoma and invasive melanoma samples, as well as Ki-67, and they had the same HMB-45, S-100, and Ki-67 invasive index." (PMID 33723350, 2021).
rheumatoid arthritis (1 paper, 2021). A chronic, systemic autoimmune disorder characterized by inflammation in the synovial membranes and articular surfaces. "Although PLA1A is likely responsible for the production of unsaturated lysoPS species, the contribution of PLA1A during the development of inflammatory diseases, such as rheumatoid arthritis (RA), remains largely unknown." (PMID 34884486, 2021).
steatosis (1 paper, 2025). Increased lipid within the cytoplasm of cells.
viral infection (1 paper, 2024). "High tissue and serum PLA1A levels have been associated with autoimmune inflammation, cancer, and viral infection, but the few studies that show in vivo PLA1A-dependent effects have not implicated GPR34." (PMID 39412501, 2024).
cancer (5 papers, 2020 to 2024). A tumor composed of atypical neoplastic, often pleomorphic cells that invade other tissues. "In this regard, the expression of PLA1A is not only restricted to inflammatory disorders but also associated with oncogenesis and cancer metastasis." (PMID 34884486, 2021). "In those patients, serum levels of PLA1A were correlated with the expression of PLA1A mRNA in the liver tissue without any carcinoma (or background tissue) but were not correlated with the PLA1A mRNA expression in carcinoma tissues." (PMID 34884486, 2021).
tumor (4 papers, 2021 to 2026). "Bioinformatics analysis revealed that APOA1, BCHE, and STARD5 were significantly expressed in normal samples, while CYP19A1 and PLA1A were considerably expressed in tumor samples in the TCGA-STAD cohort." (PMID 38357546, 2024). "mRNA and serum PLA1A levels in liquid biopsy diagnostics resulted promising tools for early diagnosis screening, tumor heterogeneity, and drug resistance of tumors with genomic mutations." (PMID 33723350, 2021). "Based on our findings, we suggest that lysoPS production from apoptotic tumor cells by stromal PLA1A may help recruit or retain cells engineered to overexpress GPR34." (PMID 41212150, 2026). "Additionally, PLA1A showed significant upregulation in tumor tissues compared with paracancerous tissues in three independent CRC cohorts including GSE44861, GSE87211, and TCGA-CRC, suggesting its potential biological relevance in CRC progression." (PMID 40740776, 2025). "In contrast, PLA1A was highly distributed over the entire tumor section and not just in the focal positive section." (PMID 33723350, 2021).
PLA1A also shares sentences with these, for which no sentence is quoted: hepatocellular carcinoma (3 papers); Alzheimer disease (2); Hepatitis (2); asthma (1); Cardiovascular Disease (1); colon cancers (1); colorectal cancer (1); COVID-19 (1); Duchenne muscular dystrophy (1); gastric cancer (1); infection (1); Intellectual disability (1); liver cirrhosis (1); lymphoma (1); metabolic syndrome (1); myopathy (1); neurodevelopmental disorder (1); neuromuscular disease (1); neuropathy (1); non-alcoholic fatty liver disease (1); osteoarthritis (1); pancreatic adenosquamous carcinoma (1); proliferative diabetic retinopathy (1); prostate carcinoma (1); sarcoidosis (1).